IGF1R (insulin like growth factor 1 receptor)
Diseases named in the same sentence as IGF1R in open-access papers (continued):
Sharing a sentence is not in itself a finding about the gene and the disease.
breast cancer (continued). "The present study aimed to analyze the differential expression of genes related to growth factors such as FGF2, FGFBP1, TGFA, TGFBR3, and IGF1R in a radiation- and estrogen-induced experimental breast cancer model." (PMID 36430763, 2022). "The field’s understanding of the role of IGF1R in breast cancer has continued to evolve over decades of study." (PMID 35784559, 2022). "WGCNA from METABRIC data revealed gene modules specific to cell cycle, adhesion, and immune cell signaling that were inversely correlated with IGF1R expression in human breast cancers." (PMID 36568144, 2022). "The regulation of IGF-1R-mediated signaling by IGFBPs in breast cancer, however, is complex, and the role of MMPs in this context has not yet been fully elucidated." (PMID 36556357, 2022). "For instance, being associated with poor outcome in breast carcinoma, TBC1D24 promoted cell proliferation through IGF1R/PI3K/AKT pathway." (PMID 35574392, 2022). "Many studies have established that IGF-1 and IGF-2 increase proliferation and growth of breast carcinoma cells in vitro, and mouse models reveal that tumor growth in distal tissues is enhanced by signaling through the IGF-1R." (PMID 36556357, 2022). "For example, IGF-1R exerts an enormous function in developing bone tumors, breast carcinoma, and colorectal cancer." (PMID 35680570, 2022). "This regulation of IGF-1R signaling in turn results in the promotion of mammary cancer cells' anchorage dependent survival." (PMID 33391524, 2021). "A recent study highlighted the benefit of a dual IGF-1R/IR inhibitor linsitinib to restore sensitivity to endocrine therapy in breast cancer." (PMID 33816477, 2021). "Co-transfection experiments in breast cancer cell lines using an IGF1R expression vector along with an IGF1R promoter-luciferase reporter construct demonstrated that IGF1R stimulated the activity of its cognate promoter." (PMID 33918477, 2021). "IGF-1R is also proposed as a prognostic breast cancer biomarker as it is found on all breast cancer subtypes to be indicative of poor prognosis." (PMID 33391524, 2021). "Our previous studies showed that IGF-1R-initiated signaling played an important role leading to Herceptin resistance in HER2-positive breast cancer cells." (PMID 33976188, 2021). "Co-transfection experiments in breast cancer cell lines harboring specific disruptions of either the IGF1R or InsR allowed us to investigate the impact of nuclear InsR on InsR gene expression." (PMID 33918477, 2021). "Nonetheless, the precise mechanism through which IGF-1R signaling is highly activated in HER2-positive breast cancer resistant to Herceptin remains elusive." (PMID 33976188, 2021). "In breast cancer, the inhibition of IGF-1R in treatment naïve breast cancer alone or in combination with cytotoxic chemotherapy has not previously been evaluated." (PMID 34611148, 2021). "IGF1R belongs to the receptor-type tyrosine kinase family and is highly expressed in many tumor cells, such as glioma, breast cancer, gastric cancer, and lung cancer." (PMID 34761108, 2021). "Glucose metabolism in Trastuzumab-resistant breast cancer cells is upregulated by the stimulation of IGF-1R heterodimerization with ErbB receptors." (PMID 34359752, 2021). "In breast cancer cells, E-cadherin downregulation hyperactivates IGF1R/IR signaling, thus enhancing sensitivity of breast cancer cells to IGF1 stimulation and Akt or ERK phosphorylation." (PMID 33673232, 2021). "Our previous study demonstrated that HRD1 inhibited the growth and metastasis of breast cancer cells by targeting IGF-1R and that it sensitized breast cancer cells to tamoxifen by targeting S100A8 for ubiquitylation and degradation." (PMID 33588886, 2021). "IGF1R and IR are frequently expressed at high levels in various malignancies such as breast cancer, colorectal cancer, and NSCLC." (PMID 34831014, 2021).
breast cancer (continued). "In in vivo breast cancer models, the inhibition of IGF-1R reduced tumor growth and increased the CD8+-mediated immune response in the tumor while reducing immunosuppressive regulatory T cells." (PMID 35008602, 2021). "In breast cancer, metabolism is, in part, responsible for metastatic spread via dysregulation of the IGF-1R/Akt pathway, which directly influences tumor progression and plays a role in the fate of anchoring metastases to the tumor microenvironment." (PMID 35008602, 2021). "In the context of cancer, the activation of IGF-1R signaling has been demonstrated to initiate the expression of stemness in breast cancer and hepatocellular carcinomas (HCC)." (PMID 34381769, 2021). "Particularly, in breast cancer, cells IGF1R and CXCR4 directly interact at the cell membrane, and this interaction allows IGF1 to promote cell migration through transactivation of CXCR4." (PMID 33673232, 2021). "Depletion of LMTK3 was shown to enhance the sensitivity of both prostate and breast cancer cells to an IGF1R inhibitor as demonstrated by a reduction in viability when exposed to an IGF1R tyrosine kinase inhibitor." (PMID 34582708, 2021). "Ultimately, the increase in the IGF-1R signaling pathway leads to tumor invasion and metastasis with evasion from the immune system, which contributes to radiation resistance and poor breast cancer outcomes in AA patients." (PMID 35008602, 2021). "Although multiple clinical trials have evaluated IGF-1R inhibitors in endocrine-resistant metastatic breast cancer, there is considerably less experience with agents targeting this pathway in operable breast cancer." (PMID 34611148, 2021). "Briefly, human IGF1R promoter fragments were labeled with biotin, followed by incubation with nuclear extracts of breast cancer cells, and purified over streptavidin beads." (PMID 33918477, 2021). "Our preclinical work shows IGF1R is lost in endocrine-resistant breast cancer and this was confirmed in a clinical trial of endocrine-resistant tumors." (PMID 33429867, 2021). "AVE-1642, a humanized anti-IGF-1R antibody, labelled with Alexa 680 has been pre-clinically investigated in in vivo breast cancer models and adequately identified receptor expression." (PMID 33535618, 2021). "IGF1R content in breast cancer (BRCA) tumors is 14 times higher than in normal tissue, and inhibiting IGF1R has been shown to block tumor growth in cell lines and model organisms." (PMID 34191793, 2021). "Clearly, while human data discourages IGF-1R targeting in breast cancer, more research is needed to get a better understanding of the potential of this approach in companion animals with mammary carcinoma." (PMID 33664868, 2021). "Phosphorylation of IGF-1R and subsequent activation of downstream signalling cascades were also found to contribute to tamoxifen resistance and drive cell proliferation in breast cancer." (PMID 33816477, 2021). "The aim of this study was to investigate the mechanism of Herceptin resistance through the IGF1R pathway in HER2 positive breast cancer." (PMID 34837929, 2021). "In a study of 438 breast cancer patients, activated IGF-1R/IR as indicated by phosphorylation status was predictive of reduced survival." (PMID 33816477, 2021). "miR-148-3p targets DNMT1 (a gene involved in DNA methylation) which regulate adipocyte differentiation and obesity and also targets WNT-1/β-catenin, AKT/ERK, IGF-1R signaling pathways in breast cancer." (PMID 33482868, 2021). "Our findings provide several insights into our understanding of the molecular basis of IGF2/IGF-1R/IRS1 signaling activation in Herceptin-resistant breast cancer." (PMID 33976188, 2021). "In vitro studies carried out on breast cancer cells showed that vitamin D treatment can downregulate the IGF-1R pathway and increase apoptosis." (PMID 35008602, 2021).
breast cancer (continued). "Lycopene has been established as an important molecule for inhibition of breast cancer cell proliferation by attenuating the insulin-like growth factor 1 receptor (IGF-1R) pathway." (PMID 34840666, 2021). "MiR-589-3p increases apoptosis and represses the invasion, migration, and proliferation of breast cancer cells by overcoming the Akt signaling through IGF1R." (PMID 34126594, 2021). "Meanwhile, overexpression of IGF-1R in transgenic mice induces mammary tumour formation through activation of Akt, Erk1/Erk2, and STAT3." (PMID 34867402, 2021). "IGF/IGF1R signaling has been reported to be involved in BM of multiple human cancers, and the PI3K/AKT and NF‐κB pathways are two downstream signaling pathways in IGF/IGF1R axis‐induced BM in PCa and breast cancer." (PMID 34185427, 2021). "In recent study, researchers found that IGF2/IGF-1R/IRS1 signaling conferred Herceptin resistance in HER2-positive breast cancer." (PMID 34837929, 2021). "Among these, the ErbB family of RTKs has been studied most extensively in breast cancer, but other RTKs such as the insulin-like growth factor 1 receptor (IGF1R) have also been explored." (PMID 34441794, 2021). "Insulin-like growth factor-1 receptor (IGF-1R) is indicated in breast cancer development, progression, and metastasis through its involvement in Ras/Raf/MEK1/2/ERK1/2 and PI3K/AKT/mTOR pathway." (PMID 33841325, 2021). "It is now understood that extensive crosstalk of IGF1R downstream signaling pathways with other breast cancer signaling pathways exists." (PMID 34441794, 2021). "The activation of the IGF-1R/Akt pathway triggers increased infiltration of the M2 macrophages, leading to tumor progression and decreased overall survival in breast cancer patients." (PMID 35008602, 2021). "Breast cancer models of activated PR lost the expression of IGF1R and acquired insulin hypersensitivity with tamoxifen insensitivity." (PMID 33144693, 2021). "miR-99a is another miRNA that can inhibit proliferation, migration, and invasion of breast carcinoma via suppression of IGF-1R." (PMID 33768092, 2021). "In vivo studies have also illustrated a significant increase in the IGF-1R phosphorylation compared to the control cells in MUC1-expressing murine breast cancer cells." (PMID 33836774, 2021). "Other described interactions include the association between syndecan-1, the insulin-like growth factor-1 receptor (IGF1-R) and αvβ3 or αvβ5 in both human mammary carcinoma cells and endothelial cells undergoing angiogenesis." (PMID 33669066, 2021). "IGF1R expression and activity increase in several tumor types, including breast cancer, resulting in enhanced proliferation rate, metastatic capacity, and resistance to chemotherapy." (PMID 32534480, 2020). "The present study provides evidence that co-treatment of IGF1R inhibitor along with chemotherapeutic drugs improves the treatment efficiency in breast cancer cells expressing high levels of IGF1R." (PMID 32391121, 2020). "This simulation tool allowed us to exploit expression data of breast cancer-derived cell lines with specific disruptions of the INSR or IGF1R genes and their targets in an extended network based on nine KEGG pathways." (PMID 32733384, 2020). "The underlying mechanism was uncovered that lncRNA NR2F1 sponged miRNA‐338‐3p to induce IGF‐1 in breast cancer cells, which further activated IGF‐1R and ERK pathway in HUVECs." (PMID 32548873, 2020). "Nuclear IGF-1R autoregulates its own expression in breast cancer cells depending on their estrogen receptor (ER) status and binds the LEF1 transcription factor, which subsequently leads to upregulated cyclinD1 and axin 2 and cell proliferation." (PMID 33584548, 2020). "IGF-1R signaling had also been demonstrated to regulate the cancer stemness in various cancer stem cell models, such as colorectal cancer and breast cancer." (PMID 33511137, 2020).
breast cancer (continued). "In this context, we have recently provided evidence that the capacity of a specific IGF1R antibody to block IGF1-mediated IGF1R activation was impaired in mutant BRCA1-expressing breast cancer cells." (PMID 32391121, 2020). "IGF1R in tumor tissue and its relevance in tumor growth and metastasis have been demonstrated in several types of cancer, such as breast cancer and pancreatic cancer." (PMID 32190664, 2020). "In our study, lncRNA NR2F1‐AS1 induced expression of IGF‐1 in breast cancer cells, which then increased the phosphorylation of IGF‐1R and ERK1/2 in HUVECs." (PMID 32548873, 2020). "Similar to the observations of decreased IGF-1R expression in TamR breast cancer cells, IGF-1R expression was decreased in MCF7-BP1 and T47D-BP1 compared to MCF7-EV and T47D-EV." (PMID 32435229, 2020). "In this regard, the portrait of genetic alterations in breast cancer support a dysfunction of the IGF-1/IGF-1R system leading to the development of various breast malignancies, including TNBC." (PMID 32325700, 2020). "Simultaneous treatment with anti-HER2 (trastuzumb) and anti-IGF1R mAbs (figitumumab) reportedly produced synergetic effects in breast cancer cells." (PMID 33083021, 2020). "Nevertheless, brain metastatic disease has not been specifically investigated in IGF1‐targeting clinical trials, although inhibition of IGF1R has been shown to reduce breast cancer brain metastasis development in experimental models." (PMID 32534480, 2020). "The stimulatory effect of hyperinsulinemia on both primary tumor growth and metastasis was demonstrated across a variety of breast cancer models employing different oncogenes with tumors showing activation of the IR/IGF-1R and Akt." (PMID 33604295, 2020). "To gain further insight into these mechanisms, we studied the expression of the tyrosine kinase receptor, IGF-1R, which is an attractive therapeutic target in breast cancer, in response to LA treatment." (PMID 31988347, 2020). "The relevance of IGF1R in tumor tissue, tumor growth, and metastasis has been demonstrated in several types of cancer, such as breast cancer and pancreatic cancer." (PMID 32190664, 2020). "We also showed that exposing breast cancer cells to the dual IGF1R/InsR inhibitor linsitinib can abrogate IGF‐1R signaling and restore endocrine therapy sensitivity." (PMID 31490549, 2020). "In summary, our study provides evidence that co-treatment of IGF1R inhibitor along with chemotherapeutic drugs greatly improves the treatment efficiency in breast cancer cells expressing high level of IGF1R." (PMID 32391121, 2020). "Based on IGFBP2 positivity of breast cancers, a DNA vaccine was designed, encoding HER-2/neu, IGFBP2 and insulin-like growth factor 1 receptor (IGF1R) as tumor associated antigens and it proved to be effective in preclinical trials." (PMID 32133294, 2020). "Hrd1 also suppressed the growth and metastasis of breast cancer cells by accelerating IGF-1R degradation." (PMID 33168784, 2020). "Breast cancer pathology specimens were evaluated for IR and IGF-1R expression by immunohistochemistry (IHC)." (PMID 32393319, 2020). "The use of a breast cancer clinical database allowed us to identify several genes whose co-expression with IGF1R also affected life expectancy." (PMID 32391121, 2020). "MCF7 breast cancer-derived cells with specific disruption of the INSR or IGF1R were used to study gene expression." (PMID 32733384, 2020). "It has recently been reported that the inhibition of IGF-1R activation and the proliferation of breast cancer cells upon tamoxifen treatment is mediated by the accumulation of extracellular insulin-like growth factor binding protein 1 (IGFBP-1)." (PMID 32435229, 2020). "For instance, high IGF-1R expression and elevated IGF-1 circulating levels have been correlated with an increased breast cancer risk and poor prognosis in breast cancer patients." (PMID 32325700, 2020).
breast cancer (continued). "This gender-specific activity was also seen in breast cancer cells where estradiol (a female-sex hormone) interacts with IGF1R to adhere to extracellular matrices as a marker of cancer progression." (PMID 32150843, 2020). "Two SNPs within two genes (rs2229765-AA [IGF1R] and rs2854744-CC [IGFBP3]) showed significant protection associations (rs2229765-AA: OR 0.82, P=.001; rs2854744-CC: OR 0.88, P=.03) for breast cancer." (PMID 32554381, 2020). "Another RTK, c-Met, is frequently overexpressed in HER2+ breast cancer patients and similar to IGF1R contributes to trastuzumab resistance." (PMID 33083021, 2020). "Little clinical evidence is available on the role of IGF‐1R expression in endocrine resistance for ER+ breast cancer." (PMID 31490549, 2020). "Next, they showed that treating breast cancer cells with linsitinib can thwart IGF‐1R signaling and restore tamoxifen's efficacy." (PMID 31490549, 2020). "Data presented here demonstrates that co-treatment of IGF1R inhibitor along with chemotherapeutic drugs markedly improves the therapeutic efficiency in breast cancer cells." (PMID 32391121, 2020). "MCF-7 is a human breast cancer cell line which expresses insulin-like growth factor 1 receptor (IGF-1R) at about 9-fold higher than that of IR23." (PMID 32382087, 2020). "The phosphorylation of the IR/IGF-1R has been noted across breast cancer sub-types, with 48.1% IR/IGF-1R phosphorylation in luminal, 64.3% in HER2-overexpressing, and 41.9% in TNBC cases examined." (PMID 33604295, 2020). "As a tumor suppressor in breast cancer, gastric cancer, pancreatic cancer and renal cell carcinoma, miR-30 prevents proliferation, invasion and metastasis by targeting IGF-1R." (PMID 32211051, 2020). "Taken together, we herein show that LA inhibits the proliferation of various ERα+ and ERα− breast cancer cell lines in vitro and ex vivo by inhibiting the maturation of IGF-1R." (PMID 31988347, 2020). "In breast cancer, the growth factor receptor IGF‐1R is frequently overexpressed, boosting cell proliferation and transformation." (PMID 31490549, 2020). "IGF‐1R and its phosphorylation status have been studied as a possible prognostic biomarker in breast cancer patients." (PMID 31490549, 2020). "We here reveal the predictive value of positive p‐IGF‐1R/InsR expression for diminished adjuvant tamoxifen benefit in a large cohort of primary ER+ breast cancer patients." (PMID 31490549, 2020). "Experiments further validated that miR-185 plays a crucial role in breast cancer by targeting Vegfa and miR-122 inhibits cell proliferation and tumorigenesis of breast cancer by targeting IGF1R." (PMID 32260218, 2020). "Igf1R mRNA expression level was similar in the two cell types; however, melanoma cells expressed almost two times more Igf2R mRNA than breast cancer cells." (PMID 32534480, 2020). "Detected by qPCR analysis, IGF1R was upregulated in breast cancer cell lines compared mammary epithelial cell lines." (PMID 32194644, 2020). "In order to prove the implication of furin in IGF-1R and IR maturation in our cellular models, we transfected ERα+ and ERα− breast cancer cell lines with furin or scramble siRNA for 48 h." (PMID 31988347, 2020). "Preclinical studies have found that hyperinsulinemia promotes the growth and metastasis of breast cancers by activating the insulin receptor (IR)/insulin-like growth factor 1 receptor (IGF-1R) signaling pathways." (PMID 32393319, 2020).